PPP1R15B-AS1 (PPP1R15B and PIK3C2B antisense RNA 1)
Synonyms: AL606489.1
Gene: Long non-coding RNA gene on chromosome 1 (204,377,258 to 204,441,465, forward strand). Ensembl gene ENSG00000226330.
Diseases named in the same sentence as PPP1R15B-AS1 in open-access papers:
PPP1R15B-AS1 is named in the same sentence as 1 disease in open-access papers, as found by Europe PMC text mining. Sharing a sentence is not in itself a finding about the gene and the disease.
PPP1R15B-AS1 shares sentences with these, for which no sentence is quoted: lung carcinoma (1 paper).